MIR9-3HG (MIR9-3 host gene)
Synonyms: BS-DRL1; lnc-FANCI-2; LINC00925
Gene: Long non-coding RNA gene on chromosome 15 (89,361,579 to 89,424,983, forward strand). Ensembl gene ENSG00000255571.
Diseases named in the same sentence as MIR9-3HG in open-access papers:
MIR9-3HG is named in the same sentence as 2 diseases in open-access papers, as found by Europe PMC text mining. Sharing a sentence is not in itself a finding about the gene and the disease. The quoted sentences say what the papers report.
cervical cancer (3 papers, 2022). A primary or metastatic malignant neoplasm involving the cervix. "LINC00925, also known as MIR9-3HG, has shown that it is strongly linked to the occurrence and development of cervical cancer in current studies." (PMID 35662687, 2022). "Although MIR9-3HG was highly expressed in cervical cancer and could regulate apoptosis in cervical cancer cells by affecting the mitochondria-mediated apoptosis pathway, a study has shown that MIR9-3HG is a protective gene." (PMID 36408157, 2022).
MIR9-3HG also shares sentences with these, for which no sentence is quoted: breast carcinoma (1 paper).